HIF1A (hypoxia inducible factor 1 subunit alpha)
Diseases named in the same sentence as HIF1A in open-access papers (continued):
Sharing a sentence is not in itself a finding about the gene and the disease.
tumor (continued). "Furthermore, hypoxia is a common characteristic feature of all rapidly growing solid tumors, which may trigger the activation of tumor-related signaling pathways such as HIF-1α." (PMID 25649293, 2015). "In tumor cells, contrastively, tanshinone-1 could not only make phosphorylation of Stat3 at Tyr705 disappear but also reduce the hypoxia-induced accumulation of HIF-1α to its baseline levels at normoxia." (PMID 26202747, 2015). "Furthermore, restoration of Nrf2 function in transformed cells decreased reactive oxygen species and impaired in vivo tumor growth (P = 0.001) by mechanisms that included sensitization to apoptosis, and a decreased hypoxic/angiogenic response through HIF-1α destabilization and VEGFA repression." (PMID 24491031, 2014). "Thus, HIF-1α expression and aerobic glycolysis are essential for tumor growth, and the inhibition of both may enhance sensitivity to anti-tumor agents." (PMID 24658058, 2014). "Interestingly, HIF-1α may promote tumor cell reprogramming into endothelium cell by regulating Twist and VE-cadherin." (PMID 25984487, 2014). "Importantly, HIF-1α is commonly upregulated in hypoxic tumour tissues, which may render resistance to radiotherapy." (PMID 24886405, 2014). "Therefore, improvement in hypoxic conditions may control tumor progression and decrease metastatic potential via regulating HIF-1α, VEGF and MMPs in SCC." (PMID 24988190, 2014). "Interestingly, PLD1-PH suppressed tumor progression and expression of HIF-1α and its target genes." (PMID 25361009, 2014). "However, we suggest the inhibition of HIF-1α expression and/or destabilization of HIF-1α using genetic manipulation or chemical inhibitors may sensitize tumor cells to IMQ-induced apoptosis for the following reasons." (PMID 24658058, 2014). "Furthermore, to investigate whether Cx43 and HIF-1α are expressed in cultured murine tumor cell lines, we first performed immunoblotting assay." (PMID 25548899, 2014). "This metabolic switch could be regulated by the activation of HIF-1α during tumor progression." (PMID 24658058, 2014). "This was further supported by experiments in TPM3-ALK (conditional onco-ALK) MEF cells which showed that both ALK and HIF1α expression are a prerequisite for miR-16 downregulation; in agreement with these findings, increased miR-16 expression in vivo reduced angiogenesis and tumour growth." (PMID 25197665, 2014). "It is also important to consider a recent report that showed that doxorubicin increased HIF-1α expression in a tumour mouse model through a STAT1-nitric oxide dependent mechanism, which suggests that certain cancer cells may have a different response to doxorubicin in vivo." (PMID 24835245, 2014). "Finally, analyses of tumor samples from mRCC patients receiving sunitinib and other targeted agents via immunohistochemistry (IHC) and other methods have examined potential markers such as hypoxia-inducible factor 1-alpha (HIF-1α)." (PMID 25100134, 2014). "Thus, it is possible that these tumor-initiating cells require the activation of HIF-1α/Notch/IGF-IR/Akt pathway, and may become sensitive to the antitumor effect of Notch inhibitors in combination with IGF-IR/Akt inhibitors." (PMID 24550888, 2014). "Therefore, a novel approach to combating tumor progression may involve specifically targeting the HIF1α/β-TRIP230-Rb complex, that regulates both angiogenic and cell invasion programs." (PMID 24919196, 2014). "Levels of HIF1α are often associated with poor patient prognosis, and taking into account the mechanism described in the study by Warfel and colleagues, this could provide one explanation for the elevation of HIF activity in tumour cells." (PMID 24858415, 2014). "Although future studies are needed to characterize the specificity of ETPs, particularly with respect to other zinc-binding proteins, the results presented suggest that directly targeting the HIF-1α/p300 complex with ETPs may be an effective approach for inhibiting angiogenesis and tumor growth." (PMID 24775564, 2014).
tumor (continued). "Furthermore, the expression patterns of LCN2 paralleled the levels of HIF-1α in tumor cells." (PMID 25467539, 2014). "Thus, this SHARP1/HIF-1α interaction may impede the ability of an EC cell to switch to an angiogenic phenotype under hypoxia, leading to suppression of tumor growth and progression in EC." (PMID 24918449, 2014). "Hence, inhibition of PHDs could prevent Hif1α degradation in normoxic conditions, a situation termed to as “pseudo-hypoxia”, which would favor tumor formation and progression." (PMID 24465590, 2014). "Effect of inhibition for tumor growth similar to case of inhibition for HIF-1α could be identified." (PMID 25068796, 2014). "In addition, the involvement of HIF-1α in TLR7/8-mediated inflammatory response in THP-1 human myeloid macrophage had been reported, but whether IMQ can modulate glucose metabolism through HIF-1α in tumor cells remains unclear." (PMID 24658058, 2014). "Therefore, to determine whether LCN2 transcript levels would increase in hypoxic tumoral regions, we analyzed the mRNA levels of LCN2 in HIF-1α-positive regions of tumor tissues by real-time RT-PCR." (PMID 25467539, 2014). "Similarly, regulation of KDM3A by HIF1α enhances hypoxic gene expression and tumour growth." (PMID 24858415, 2014). "Thus, increased HIF-1α activity resulting from loss of Cx43 expression may also contribute to the overexpression of VEGF, which is observed in our system tumor models." (PMID 25548899, 2014). "Therefore, we hypothesized that miR-18a might affect tumor growth and metastasis by targeting HIF1A." (PMID 25069832, 2014). "Whether HIF-1α can promote tumor cell apoptosis or antiapoptosis has been controversial." (PMID 25105148, 2014). "In addition, HIF-1α indirectly reflects the extent of tumor oxygenation." (PMID 24669250, 2014). "We investigated whether hypoxia could promote tumor invasion and migration via HIF-1α and LOX." (PMID 23545606, 2013). "HIF-1α is highly expressed in human cancers as a result of intratumoral hypoxia as well as genetic alterations, such as gain-of-function mutations in oncogenes (for example, ERBB2) and loss-of-function mutations in tumour-suppressor genes (for example, VHL and PTEN)." (PMID 23382894, 2013). "However, whether HIF-1α promotes tumor cell apoptosis or has anti-apoptotic affects is controversial." (PMID 23426939, 2013). "The results indicate that Annexin A3 may be involved in tumor angiogenesis by regulating HIF-1α." (PMID 24260057, 2013). "We investigated whether NMB-R and HIF-1α expression correlate in tumor xenografts." (PMID 24349381, 2013). "In this experimental set-up, we observed a mesenchymal to epithelial-like transition, which might explain the inability of EGFR-CD533 expressing tumor cells to escape from hypoxic areas through invasion and instead induce an angiogenic program by upregulating HIF1A." (PMID 23429996, 2013). "This suggests that the crosstalk between HIF-1α and mitochondria plays a prominent role in restoring and maintaining mitochondrial bioenergetics when BCCs are exposed to intermittent hypoxia in the tumor microenvironment as well as during invasion and metastasis." (PMID 23840849, 2013). "Since HIF-1α has recently been implicated in PR-mediated VEGF synthesis, we undertook studies to determine whether YC-1 inhibits progestin-dependent VEGF induction and tumor progression." (PMID 23123638, 2013). "HIF-1α is a transcription factor that activates transcription of genes involved in anaerobic metabolism, angiogenesis, survival, invasion, metastasis and treatment resistance in tumor cells, thus promoting cellular adaptation and survival under hypoxic conditions." (PMID 24179495, 2013). "Thus, HIF-1α acts as a positive regulator of tumor development." (PMID 23426939, 2013). "Furthermore, most high HIF-1α tumor cells were high expression of TGF-β1." (PMID 23723999, 2013).
tumor (continued). "Thus, tumor hypoxia induces an accumulation of HIF-1α, which in turn increases the expression of integrin α5 and fibronectin in the tumor cells, facilitating binding to the ECM that is rich in fibronectin, and providing cell invasion potential at the cell surface." (PMID 24137322, 2013). "Importantly, previous studies suggest that YC-1 may have significant anti-tumor activity by targeting HIF-1α and NF-κB transcription factors." (PMID 23123638, 2013). "Therefore, a strategy to inhibit the hypoxic tumor response may be to target the binding and subsequent interaction of HIF1α CTAD and p300/CBP CH1 domains." (PMID 23671581, 2013). "Interestingly, elevated STAT3 activity can increase HIF-1α promoter activity in both cancer cells and nontransformed, tumor-associated myeloid cells in the TME." (PMID 24314323, 2013). "Hence, one possibility is that the involvement of constitutive PI3K/Akt signaling in hypoxic activation of HIF-1α may depend on cell type or on tumor type/stage and its microenvironment." (PMID 23590596, 2013). "P70S6K1 may regulate HIF-1α expression and tumor angiogenesis." (PMID 23437196, 2013). "Immunohistochemical analyses in vivo showed that, when tumor-bearing mice were continuously administered glucagon, which increases blood glucose concentrations and so improves glucose-availability in the pimonidazole-positive hypoxic regions, HIF-1α expression was dramatically induced there." (PMID 23203043, 2012). "Furthermore, HIF-1α overexpression contributed to the generation of tumor stem-like cells." (PMID 23391506, 2012). "On the other hand, HIF-1α was not necessarily associated with prognosis of the surgically treated supraglottic carcinoma cases, while it was positively correlated with the T-classification of tumor." (PMID 23762617, 2012). "Therefore, we investigated whether 17-AAG- or NVP-AUY922-induced changes in HIF-1α levels determine the radiosensitivity of the tumor cells exposed to hypoxic conditions ([O2] = 0.66%) prior to irradiation." (PMID 22347438, 2012). "However, a few studies have described the tumor-suppressor functions of HIF-1α." (PMID 23181099, 2012). "Importantly, KAI1 inhibited the expression of CDCP1 and HIF-1α in an in vivo tumor xenograft model." (PMID 22390300, 2012). "Therefore, it was assumed that genetic alterations in oncogenes and/or tumor suppressor genes might be involved in the tumor cell type-specific regulation of HIF-1α." (PMID 22347438, 2012). "How HIF-1α directly affects various tumor cell subpopulations defined through flow cytometric profiling for the known murine mammary stem cell markers, or whether HIF-1α is preferentially expressed in a given subpopulation requires further extensive investigation." (PMID 22225988, 2012). "Then, we next examined whether cancer cells in the pimonidazole-positive/HIF-1α-negative layer actually survive radiation therapy and directly cause tumor recurrence." (PMID 23203043, 2012). "This may justify PHD2 inability to regulate HIF-1α level in some normoxic tumor types." (PMID 23077544, 2012). "However, dual effects of HIF-1α in regulating tumor cell survival have been described." (PMID 22347438, 2012). "Thus, HIF-1α is a key downstream target of miR-21 in the regulation of tumor angiogenesis." (PMID 22952749, 2012). "An increase in HIF-1α protein levels caused by accumulation of succinate and inhibition of PHD enzymes has been described in diet-induced ketotic as well as in 3-hydroxybutyrate-infused rat brain and would probably be a rather unwanted effect regarding tumor treatment." (PMID 21791085, 2011). "Thus, the downregulation of the activity of HIF-1α could have an immediate effect on its target genes contributing to blocking tumor angiogenesis, glycolysis and tumor growth and also improve the efficacy of classical therapies." (PMID 21248371, 2011).
tumor (continued). "Thus above findings also have another implication that regulating micro-environment redox status in hypoxic tumor cells may be beneficial to tumor chemotherapy by reduction of the expression of MDR-1 dependent upon HIF-1α." (PMID 21595915, 2011). "In addition, the dynamics of HIF-1 signal transduction activity mediated by cyclic hypoxia in a tumor is fast due to the instability of the HIF-1α protein under reoxygenation; a reporter gene with a high temporal resolution is required for monitoring such dynamic processes." (PMID 21935366, 2011). "Therefore, our data indicate that the changes of redox status in hypoxic cells may regulate HIF-1α expression and provide valuable information on tumor chemotherapy." (PMID 21595915, 2011). "Therefore, we propose that targeting HIF-1α may provide a broader inhibition of tumor angiogenesis than targeting downstream angiogenesis factors of HIF-1α." (PMID 21843314, 2011). "In addition, our data suggest that HIF-1α plays a role in the survival and self-renewal potential of CSCs and identify genes that might further elucidate the role of HIF-1α in tumor migration, invasion and stem cell biology." (PMID 20515450, 2010). "However, it could be speculated that expression of HIF-2α, in manipulated CCRCC 786-0 tumors, overcomes the HIF-1α effects, which results in a more oxidative tumor phenotype that supports a more aggressive phenotype." (PMID 20652061, 2010). "As, we have shown here, the NE differentiated tumor cells display an isoform with a possible inhibitory effect on the wild type HIF1α protein, indicating that the androgen independent malignant NE cells might also be independent of HIF1α for their survival and tumorogenesis." (PMID 20663134, 2010). "Moreover, targeting HIF-1α could be an attractive therapeutic strategy with the potential for disrupting multiple pathways crucial for tumour growth." (PMID 20565904, 2010). "However, HIF1α also has a role in addition to HIF2α in promoting tumour growth." (PMID 20104230, 2010). "Likewise there was a significant up-regulation of TSP1 protein coupled with a down-regulation of HIF1α protein, androgen receptor protein (AR), and glucose transporter-1 protein (i.e. down stream target of HIF1α) within tasquinimod treated tumor tissues excised and prepared on day 28 (p < 0.05)." (PMID 20470445, 2010). "The induction of hypoxia inducible factor (HIF-1α) by hypoxia, subsequently leads to the transcriptional activation of genes encoding erythropoietin, VEGF and glycolytic enzymes, all thought to be involved in various aspects of tumour initiation, growth and metastasis." (PMID 21190577, 2010). "Thus, the expression miR-20b is inversely relative to the level of HIF-1α protein in tumor cells, implying that tumor cell HIF-1α might be a target of miR-20b." (PMID 19893619, 2009). "On the basis of its unquestioned role as a central regulator of tumor pathophysiology, elucidating HIF-1α's prognostic value in HCC is of great clinical importance, which may lead to better patient stratification and provide rational for hypoxia targeted therapies." (PMID 19948069, 2009). "We have recently shown that BMP2 in vitro treatment, known to promote glial differentiation in GBM derived cells, resulted to be less effective under hypoxia, suggesting that hypoxia and also HIF-1α may preserve GBM tumour cell stemness by de-sensitizing cells to pro-differentiating BMP2 stimulus." (PMID 19587783, 2009). "Thus, HIPK2 inhibition by RNA interference induces HIF-1α up-regulation and tumor angiogenesis." (PMID 19714248, 2009). "In addition, we transfected VHL siRNA to normoxic tumor cells to increase the HIF-1α protein level." (PMID 19893619, 2009). "As HIF-1α is known to be rapidly degraded under oxygen-available conditions, we postulated that a radiation-induced improvement of oxygen availability (tumour reoxygenation) was involved in the temporary decrease in HIF-1α expression and HIF-1 activity at 6 h postirradiation." (PMID 19223896, 2009).
tumor (continued). "However, the distribution of the active, endonuclear HIF-1α form in the tumor was not haphazard, but strongly associated with histological features such as necrosis and severe peritumoral inflammation." (PMID 18983642, 2008). "Elucidation of the mechanism(s) responsible for VEGF and PlGF induction will require further study, but it is reasonable to speculate that treatment-related increases in tumor hypoxia may be involved, perhaps via increased activity of HIF-1α or other hypoxia-inducible factors." (PMID 17605814, 2007). "Also, HIF-1α phosphorylation status may determine whether it acts to promote or check tumour cell survival." (PMID 17179985, 2007). "Therefore, the prognostic effect of HIF-1α expression in tumour locations more representative of the UK population remains unknown." (PMID 17179985, 2007). "Our data indicates that downregulation of HIF-1α is associated with positive therapeutic responses of cancer cells to EGFR-targeted therapy and suggest further investigation using HIF-1α as an indicator of tumor response to EGFR-targeted therapy in preclinical studies and in the clinical setting." (PMID 17931419, 2007). "Although HIF-1α-dependent transcriptional activation has been associated with tumor growth, our results suggest that concomitant expression of p21 and HIF-1α may retard tumor growth to some degree." (PMID 17166265, 2006). "HIF-1α-expression could be detected in the tumour stroma in only 5 cases." (PMID 16035955, 2005). "Thus, 40 tumours (30.8%) were classified as showing high HIF-1α expression." (PMID 12966423, 2003). "FAs released from adipose tissue activate HIF‐1α in cancer cells, which in turn increases the secretion of CCL2, promoting tumor growth and metastasis." (PMID 41160815, 2026). "A consistent pattern emerged, supporting previous findings: the expression levels of HIF‐1α, CCL2, and Ki67 in tumor tissues increased progressively with higher BMI." (PMID 41160815, 2026). "In hepatocellular carcinoma, the HIF-1α/METTL16/lnc-CSMD1-7/RBFOX2 signaling axis has been shown to regulate interactions between tumor cells and the tumor microenvironment, particularly influencing cell behaviors such as epithelial–mesenchymal transition." (PMID 41459114, 2026). "Key molecular drivers include HIF-1α, VEGF, bFGF, and β-catenin, promoting tumor growth via pathways like Wnt/β-catenin and Ras signaling." (PMID 41892175, 2026). "Given this potential tumor-suppressive function of HIF-1α in normoxic TNBC cells, caution should be exercised when developing therapeutic strategies aimed at inhibiting HIF-1α signaling." (PMID 41526224, 2026). "Given that HIF-1α, a key upstream inducer of VEGF, plays a crucial role in tumor angiogenesis, we quantified VEGF and HIF-1α expression in HUVECs by qPCR." (PMID 41596235, 2026). "Immunohistochemical staining was performed on surgical specimens to assess tumor (HIF-T%) and stromal (HIF-N%) HIF-1α expression, and correlations with postoperative pathological stage were analyzed." (PMID 42193129, 2026). "Nuclear and cytoplasmic HIF1A and EPAS1/HIF2A expression were assessed by immunohistochemistry in tumours from 40 patients and correlated with clinicopathological parameters and cancer-specific survival." (PMID 42074150, 2026). "In hypoxic tumor niches, YAP/TAZ activity is sustained through HIF-1α and Snail upregulation, which inhibit LATS1/2 kinases and maintain YAP/TAZ in an active state." (PMID 41596432, 2026). "IL6/IL6R/STAT3 and HIF1α/ZEB1 pathways induce epithelial to mesenchymal transition (EMT) and CAFs secrete EGF, FGF and HGF for tumour growth." (PMID 41476776, 2026).